EGFR (epidermal growth factor receptor)
Diseases named in the same sentence as EGFR in open-access papers (continued):
Sharing a sentence is not in itself a finding about the gene and the disease.
infection (continued). "To investigate the role of EGFR in the infection of host cells by IAV, we immobilized fluorescently labeled IAV PR8 particles on glass surfaces and cultured A549 cells expressing endogenous levels of EGFR-GFP on top of these viruses." (PMID 40280912, 2025). "Previous work has linked activation of S6 kinase and mTOR signaling through EGFR activation during HPV and MmuPV1 infection." (PMID 41165329, 2025). "Studies have shown that inhibition of EGFR signaling reduces infection of SARS-CoV-2 (Severe Acute Respiratory Syndrome Coronavirus 2)." (PMID 41139925, 2025). "During infection, EGFR is first phosphorylated at Tyr845, which is carried out by c-Src kinase transmitting a signal from nearby receptors." (PMID 40362195, 2025). "Previous studies have demonstrated that EGFR activation plays a key role in the infection of many respiratory viruses, including SARS-CoV-2." (PMID 40872743, 2025). "Intriguingly, an observed decrease in total EGFR levels upon WT-VACV infection or VGF/EGF treatment warrants further investigation." (PMID 39817770, 2025). "Parental CHO cells, confirmed to be devoid of EGFR as assessed by real-time quantitative PCR and immunoblot, exhibited Src phosphorylation at Tyr416 (marker of Src activation) after infection with T. gondii." (PMID 39869638, 2025). "RSV, in its early infection stage, activates EGFR-driven survival signaling and directs the mitochondrial translocation of EGFR, thereby prolonging its functional state." (PMID 41020817, 2025). "EGFR colocalized with virions at early time-points of infection, and the ED3 domain of the JEV-envelope protein showed specific interaction with EGFR through Bio-layer interferometry (BLI)." (PMID 41401233, 2025). "The activation of the EGFR-ERK signaling cascade during the early time of infection was also related with suppression of the interferon response in hBMECs." (PMID 41401233, 2025). "Recently, several small-scale meta-analysis studies were published to compare the safety of a few EGFR-TKIs (Osimertinib, Erlotinib, and Gefitinib) or individual adverse reactions (diarrhea, infection, rash)." (PMID 40949148, 2025). "Previously, EGFR was suggested as a potential candidate glycoprotein involved in infection of IAV PR811." (PMID 40280912, 2025). "Taken together, these results indicate that SARS-CoV-2 activates the EGFR signal cascade and enhances the mitochondrial localisation of EGFR during the early stage of infection." (PMID 38734691, 2024). "In these assays, mock infection and LacZ expression serve as erlotinib-sensitive controls, while expression of EGFR T790M, with an otherwise WT kinase domain, is an erlotinib-insensitive control." (PMID 38548752, 2024). "Taken together, these data indicate an association between EGFR-mediated signalling and the proliferation of SARS-CoV-2-infected cells during the early stage of infection." (PMID 38734691, 2024). "Our results indicated that both at 48 h and 72 h post-infection, EGFR knockdown cells exhibited significantly higher viral titers." (PMID 39336799, 2024). "EGFR plays critical role in the regulation of inflammation and infection through various mechanisms." (PMID 38632608, 2024). "In uninfected mice, minimal phosphorylation of EGFR was detected in the pulmonary epithelial cells, whereas in mice infected with A. fumigatus there was substantial EGFR phosphorylation at foci of infection." (PMID 39314401, 2024). "And we also found that, at 48 h post infection, the majority of EGFR and a small fraction of E2 ended up on the cell surface, while the majority of E2 was intracellular." (PMID 38253527, 2024). "Long-term post-MHV-1 infection was associated with increased protein levels of HIF1-α, TLR-2, and EGFR, as revealed by immunoblot investigations." (PMID 38672267, 2024). "As an adhesin of C. psittaci, Pmp17G binds to multiple host cells and promotes chlamydial adhesion in an EGFR-dependent manner during early infection." (PMID 39541409, 2024).
infection (continued). "To investigate the activation of the EGFR and MAPK ERK1/2 pathways, we confirmed EGFR and ERK phosphorylation after infection with the variant pseudoviral particles and compared it with that after infection with WT pseudoviral particles." (PMID 39291996, 2024). "Previous studies have established that the EGFR pathway plays a pivotal role in the infection mechanism of WT SARS-CoV-2." (PMID 39291996, 2024). "Activation of the EGFR and ERK1/2 pathways was increased in hACE2-HEK293 cells following infection with the variants compared with that after infection with WT pseudoviral particles." (PMID 39291996, 2024). "When the fungus interacts with these cells, EGFR is activated, leading to the production of proinflammatory cytokines and chemokines that recruit leukocytes and dendritic cells to foci of infection where they can kill the fungus." (PMID 39314401, 2024). "The stability of EGFR was decreased by inhibition of RSV replication when exposed to vandetanib for 16 h post-infection." (PMID 38139259, 2023). "The Western-blot results indicated that the level of p-EGFR increased significantly during the pre-PEDV infection stage (10, 30, and 60 min) compared with the control group." (PMID 38029193, 2023). "RSV activates the intracellular EGFR-mediated cell survival signaling cascade and maintains mitochondrial EGFR expression for viral production during early events after infection." (PMID 38139259, 2023). "This validates our conjecture that EGFR can be involved in PEDV invasion of IPEC-J2 cells and that EGFR activation induced by PEDV infection enhances the ability of PEDV to infiltrate." (PMID 38029193, 2023). "To confirm this data in a more authentic cell culture system, we used induced pluripotent stem cell (iPSC)-derived hepatocyte-like cells (HLCs) and transduced these with short hairpin RNA targeting EGFR (shEGFR), followed by infection with HEVcc (p6)." (PMID 36745934, 2023). "In order to further study the mechanism of PEDV regulating NHE3, the expression of key signaling factors in NHE3 and EGFR pathways was detected by regulating the activity of EGFR after infection with PEDV." (PMID 38029193, 2023). "The intensity of the EGFR bands in BALF was reduced in mice administered NE inhibitor after infection compared with the infected group." (PMID 37119853, 2023). "The host epidermal growth factor receptor (EGFR) signaling was activated during infection, and the alveolar epithelial cell EGFR (using A549 cell line) was also phosphorylated when interacting with several Mucorales organisms." (PMID 37808914, 2023). "Based on this, our study used porcine intestinal epithelial cells (IPEC-J2) as an infection model to investigate the role of EGFR in regulating NHE3 activity after PEDV infection." (PMID 38029193, 2023). "Upon VACV infection, VGF-induced EGFR activation and F1L co-operate to maintain cell survival against infection-induced apoptotic activity." (PMID 38136637, 2023). "Previously, we have shown that the treatment of M-HeLa cells with the EGFR inhibitor reduced the invasion of S. proteamaculans but increased the infection with S. grimesii at an MOI of 100 by 1.5 times." (PMID 38069398, 2023). "Immunoblot studies showed an elevation in protein levels of HIF1-α, TLR-2, and EGFR long-term post-MHV-1 infection." (PMID 37626956, 2023). "Other studies also found a prominent role of the epidermal growth factor receptor (EGFR) in promoting the infection and serving as a target for antifungal drugs such as cetuximab or gefitinib." (PMID 36983503, 2023). "Activation of AKT at early stages of infection in HBMEC was shown to be triggered via EGFR autophosphorylation by T. gondii microneme (MIC) proteins MIC3 and MIC6, both adhesins harboring EGF‐like domains." (PMID 37387601, 2023). "This study revealed that RSV activates an EGFR-mediated cell survival cascade during the early stages of infection and induces the translocation of EGFR to the mitochondria, where it maintains its activity." (PMID 38139259, 2023).
infection (continued). "To verify that the inhibitors blocked the phosphorylation of c-Met and EGFR, we used phosphospecific antibodies to label the tongues of immunosuppressed mice after 5 days of infection with wild-type C. albicans." (PMID 37611070, 2023). "EGFR is NTCP’s co-receptor, which internalizes the HBV-NTCP-EGFR complex such that it is co-localized intracellularly upon infection." (PMID 37892121, 2023). "Specifically, KIM1 and MMP7 protein levels are significantly increased in acute MHV-1 infections, while a significant increase in EGFR protein level was identified long-term post-infection." (PMID 37626956, 2023). "Activation of EGFR signaling occurs via virus binding and is immediately inhibited in the early stages of infection." (PMID 38136637, 2023). "Although the overall expression of EGFR remained consistent before and after drug treatment, a reduction in p-EGFR expression was observed at 60 min post-infection." (PMID 38139259, 2023). "Our results are in line with results of Minutti, where infection of mice with H. polygyrus resulted in an increased number of CD4+ T cells with EGFR expression in duodenum, MLN, and spleen." (PMID 36836678, 2023). "Given that hepatocytes are the main target of HEV during infection, we aimed to address the role of endogenous EGFR on HEV infection." (PMID 36745934, 2023). "Our observations revealed the localization of RSV-NPs and EGFR to the mitochondria, with RSV-induced mitochondria-activated EGFR phosphorylation at 16 h post-infection." (PMID 38139259, 2023). "EGFR signaling is a central pathway required for SARS-CoV-2 replication, and EGFR inhibition has emerged as a novel strategy to suppress endogenous antiviral defenses during host infection by respiratory viruses and PEDV." (PMID 36366532, 2022). "To validate the results of the in vitro experiments, we detected the RNA levels of miR-147, MSI1, KIAA1199, NF-κB p50, and EGFR in the cancerous tissues of chickens in different infection groups, including the bone marrow, liver, and heart." (PMID 36291177, 2022). "CMV interferes with host cell signaling and downregulates epidermal growth factor receptor (EGFR) and its downstream pathways during early stages of infection in order to establish latency." (PMID 36338037, 2022). "The host epidermal growth factor receptor (EGFR) is phosphorylated, activated, and colocalized with Mucorales fungi during infection." (PMID 35806905, 2022). "After 2 h of infection, the transcriptional upstream regulators EGFR, EGR1, FOXL2, FOXO3, IL1A, IL1B and RELA were activated in MKN-28 cells infected with either H. pylori wt or the ΔhtrA mutant, while WWTR1 was inhibited." (PMID 37193047, 2022). "Taking all these observations together, these results suggested that JEV infection activates EGFR through phosphorylation at the early stage of infection." (PMID 35847084, 2022). "Many viruses activate EGFR through phosphorylation at the early stage of infection, including ZIKV, PEDV, and IAV." (PMID 35847084, 2022). "After LV-CAV1 infection, phosphorylation of EGFR and ERK decreased significantly and autophagic flux was restored." (PMID 35886933, 2022). "Contrariwise, it seems that the release of HBD-3 from H. pylori infected cells occurs during the early stage of this infection via a new Epidermal growth factor receptor (EGFR)-activating." (PMID 35740732, 2022). "We found that infections with standard C. albicans SC5314 and drug resistant strain 1052 can induce high level of phosphorylated EGFR in collected vaginal tissues, especially in the case of 1052 infection." (PMID 35720274, 2022). "EGFR is also an important factor ensuring efficient cell type and tissue-specific infection, as either a native or molecularly targeted host cell co-receptor, in multiple gene therapy applications." (PMID 35083168, 2021).
infection (continued). "Global proteo-metabolomics profiling indicated the upregulation of host factors predominantly associated with ATP turn over, glycolysis, urea cycle, which ultimately promote the activation of EGFR-HIF1α signaling upon infection." (PMID 33868285, 2021). "Following infection, we examined EGFR mRNA levels via real-time PCR and EGFR protein levels via Western blot analysis." (PMID 34944046, 2021). "Lactobacillus rhamnosus GG (LGG) can stimulate intestinal epithelial cells to secrete APRIL by activating EGFR, thus promoting the production of intestinal anti-infection antibody lgA." (PMID 34916934, 2021). "We showed that infection with the S. proteamaculans leads to an increase in β1 integrin and EGFR expression by 2–2.5 times." (PMID 34948042, 2021). "Overall, these in vivo observations ascertained that EGFR-HIF1α is essential to establish infection in vivo." (PMID 33868285, 2021). "This unique signaling pathway suggests that HCMV-infected monocytes use a distinctive mechanism in infected monocytes to promote productive infection and that this process is controlled by pentamer/integrin and gB/EGFR engagement." (PMID 34025614, 2021). "This implies that EGFR downstream pathways are regulated by E2, and it can influence oncogenesis at late stage of infection." (PMID 34646755, 2021). "Comparison of cell infection profiles in the presence of Erlotinib, an EGFR inhibitor, revealed that the receptor activation is required for the antibacterial but not for the antiviral protein action." (PMID 33226440, 2021). "In contrast, viruses such as HSV-1 and vaccinia virus subvert EGFR signaling to facilitate their infection." (PMID 33996800, 2021). "Currently, two major oncogenic pathways were described for SNSCCs—infection by high-risk human papilloma virus (HR-HPV) and constitutively activating Epidermal-Growth-Factor-Receptor (EGFR) mutations." (PMID 34885191, 2021). "Gefitinib treatment induced proteomic and metabolomic reprogramming of Salmonella infected macrophages, indicating that Salmonella utilizes EGFR signaling to modulate host protein and metabolites to establish infection." (PMID 33868285, 2021). "The cell's ability to mount an effective immune response was greatly diminished when inhibiting EGFR, thus inhibiting LD upregulation during infection, also leading to an increase in viral replication." (PMID 34527863, 2021). "After treatment with EGFR siRNA, the relative infection was reduced dramatically compared to that of the control siRNA and the mock groups." (PMID 35173712, 2021). "EGFR is a well-studied viral entry receptor that contributes to the establishment of efficient infection and latency of both monocytes and CD34+ HPCs." (PMID 34663377, 2021). "Previously, we found that infection of oral epithelial cells with viable C. albicans induces sustained phosphorylation of both EphA2 and EGFR, leading to the secretion of proinflammatory mediators." (PMID 33471869, 2021). "It has been shown that in human bronchial epithelial cells treated with SARS-CoV, for 12, 24, and 48 h, the expression of EGFR gene is increased 12 h after the infection and then decreases after 24–48 h." (PMID 33379366, 2020). "Consistent with recent findings for HCMV entry, we have shown that TB40/E infection of human brain organoid involves PDGFRα and EGFR as cellular receptors either directly or indirectly, whereas the infection does not appear to involve cellular integrins." (PMID 33205055, 2020). "The mechanism by which EGFR signaling promotes HSV-1 and VZV replication during productive infection, and the role of EGFR signaling in neuronal latency will be intriguing avenues to follow-up in future studies." (PMID 32547533, 2020). "Using an immunoblotting assay, we determined that infection with R. delemar induces EGFR phosphorylation in A549 cells." (PMID 32487760, 2020).
infection (continued). "The gene expression of EGFR and a group of other genes were transiently downregulated from 5 to 20 h post-infection and from 20 to 48 h post-infection by IAPV." (PMID 33101388, 2020). "After 24 h of infection, EGFR siRNA transfected cells tended to be yellow, whereas control siRNA transfected cells were predominantly red, reflecting less fusion of autophagosomes with lysosomes upon EGFR siRNA transfection compared with control siRNA." (PMID 31896739, 2020). "Since EGFR signaling is regulated during lytic infection and is important for latency and reactivation in CD34+ HPCs (5, 14, –, 16, 31), we examined EGFR signaling pathway members as potential targets of HCMV miRNAs." (PMID 32759334, 2020). "Initially, we verified that our IAV strain (H3N2/X31) binds to and depends on EGFR for cell infection in our experimental system." (PMID 32639985, 2020). "Quantitative analysis indicated that phospho-EGFR(Y1068) levels increased approximately 6.5, 13.3, and 25.3-fold after infection for 24, 36, and 48 h, respectively." (PMID 32846937, 2020). "We demonstrate that CMV downregulates EGFR early in the productive infection, which blunts the activation of EGFR and its downstream pathways in response to stimuli." (PMID 31725811, 2019). "As previously reported, infection with E. coli increased the number of EGFR-expressing PBMO and CBMO." (PMID 32082070, 2019). "Adv-DN-Akt infection resulted in decreased P-Akt, total Akt and P-EGFR contents irrespective of the presence of CDDP, suggesting that Akt is also an upstream of EGFR and is associated with its activation." (PMID 31360122, 2019). "Confocal imaging revealed that EGFR accumulated in intracellular vesicles following infection with HAdV-C2, in contrast to mock-treated cells where EGFRs were predominantly associated with plasma membrane." (PMID 31425554, 2019). "HAdV-C2 infection also led to rapid EGFR phosphorylation at residues Ser1046/1047, which are substrates for the p38-MAPK effector MK2 (mitogen-activated protein kinase-activated protein kinase 2) that is known to be activated by viral cell entry." (PMID 31425554, 2019). "To rigorously rule out a role for the RIDα protein in these early responses, we showed that the RIDα-null mutant virus led to the same site-specific EGFR and NFκB-p65 phosphorylation events within the first 90-min of infection." (PMID 31425554, 2019). "Contrary to infection of fibroblasts that support virus replication, EGFR cell surface levels are transiently increased during infection of CD34+ cells." (PMID 31725809, 2019). "Whereas the percentages of infected cells were similar in both groups of mice at 2 h post-challenge, endothelial cells from Trg-DN EGFR mice exhibited a marked reduction in the percentages of infection at 24 h." (PMID 30679495, 2019). "We also provided evidence suggesting that the ATP1A1-Src-EGFR signaling occurs predominantly in the cholesterol-rich domains of the caveolae which are thus important for efficient infection." (PMID 31381610, 2019). "The lysates were analyzed using an EGFR phosphorylation array to identify the EGFR sites that were phosphorylated during infection." (PMID 31381610, 2019). "We previously demonstrated that CMV modulates EGFR total and cell surface levels during infection in fibroblasts (productive infection) and CD34+ HPCs (site of latency)." (PMID 31725811, 2019). "In fibroblasts, EGFR surface and total levels decrease substantially by 48 hours post infection (hpi)." (PMID 31725811, 2019). "This is in line with previous results showing that EGFR density (MFI) significantly increases after infection with E. coli." (PMID 32082070, 2019). "Analysis was conducted on day 7 post-infection, a time point when there is already decreased T. gondii load in the brain of Trg-DN EGFR mice." (PMID 30679495, 2019). "T. gondii induces phosphorylation of the tyrosine residues 1,068, 1,148, and 1,173 of EGFR during infection of human or rodent cells." (PMID 31119109, 2019).